ERBB4 (erb-b2 receptor tyrosine kinase 4)
Diseases named in the same sentence as ERBB4 in open-access papers (continued):
Sharing a sentence is not in itself a finding about the gene and the disease.
schizophrenia (continued). "Many studies using mouse models of NRG1 and ErbB4 have shown schizophrenia-related behaviors that can be reversed using antipsychotic drugs." (PMID 26733804, 2015). "Post-mortem brain analyses and some genetic studies have reported interneuronal deficits and involvement of the DISC1, NRG1 and ErbB4 genes in schizophrenia, respectively." (PMID 26656849, 2015). "NRG3 is a neurotrophic factor, a specific ligand for the receptor tyrosine kinase ErbB4 and a paralog of the growth factor NRG1, all of which are strong candidate risk genes for schizophrenia." (PMID 25093331, 2014). "Genetic evidence also supports ERBB4 – the NRG1 receptor – as a candidate susceptibility gene and suggests positive epistatic interactions between NRG1 and ERBB4 in schizophrenia." (PMID 24478629, 2014). "Manipulation of NRG1 and ErbB4 in rodents leads to behavioral and neurophysiological phenotypes relevant to schizophrenia, consistent with their known roles in neuronal development, myelination and neurotransmitter function." (PMID 25093331, 2014). "We found a decrease in TrkB/ErbB4 interaction in the prefrontal cortex of schizophrenia subjects as compared to controls." (PMID 25052836, 2014). "Following immunoprecipitation with TrkB, prefrontal cortical lysates from schizophrenia and control subjects were examined for ErbB4 levels." (PMID 25052836, 2014). "Genetic association analysis showed that OLIG2 is associated with schizophrenia and demonstrated an epistatic effect with 2′,3′-cyclic nucleotide 3′-phosphodiesterase (CNP) and ERBB4." (PMID 24478629, 2014). "Several studies have investigated the impact of single nucleotide polymorphisms (SNPs) and haplotypes of ERBB4 and NRG1 on the risk of developing schizophrenia." (PMID 23301017, 2013). "Genetic manipulation of schizophrenia susceptibility genes in rodents, such as DISC1, NRG1/ErbB4, and COMT has been largely explored as well." (PMID 24027504, 2013). "With respect to candidate ERBB4 region, binding of USF and deltaE, instead of NKX2, was associated with a protective role in schizophrenia, which was due in part by the rs7589006 variant within the 4-SNP haplotype." (PMID 23301017, 2013). "The possible mechanisms by which altered function of NRG1 and its receptor ErbB4 contribute to schizophrenia have been reviewed by Mei and Xiong." (PMID 23618463, 2013). "In this study, we utilized a haplotype-based approach to systematically screen for novel associations, as well as to validate the previously reported variations within ERBB4 and NRG1 that conferred risk of developing schizophrenia." (PMID 23301017, 2013). "Among these genes were ERBB4 and NRG1, providing further support for a role of these genes in schizophrenia susceptibility." (PMID 22253750, 2012). "In this study we sequenced all coding regions of ERBB4, a candidategene with strong biological plausibility, as well as suggestive evidence for geneticassociation with schizophrenia." (PMID 21637803, 2011). "Mice hypomorphic for NRG1 or ErbB4 show behavioral abnormalities consistent with existing animal models for schizophrenia, including abnormal prepulse inhibition and enhanced response to cannabinoid and dopaminergic agonists." (PMID 22028923, 2011). "For instance, recurrent CNVs involving the putative schizophrenia risk genes NRXN1 and erbB4 are reported in control populations." (PMID 22547958, 2011). "In the functional studies, mutant mice heterozygous for either NRG1 or its receptor erbB4 showed a behavioral phenotype that overlaps with mouse models for schizophrenia." (PMID 22937274, 2011). "Although ERBB4 has been far less studied than NRG1,preliminary evidence suggests a possible association with schizophrenia." (PMID 21637803, 2011). "Post-mortem studies havealso provided initial evidence for a functional interaction of ERBB4 with the NMDAreceptor, alsoa promising therapeutic target for both mood disorders and schizophrenia." (PMID 21637803, 2011).
schizophrenia (continued). "Putative candidate schizophrenia genes like neuregulin/ErbB4 and reelin have important roles in migration of new neurons, and some studies have implied a reduction in neurogenesis in the schizophrenic brain." (PMID 21966452, 2011). "The Neuregulin-ErbB4 pathway plays a crucial role in brain development andconstitutes one of the most biologically plausible signaling pathways implicatedin schizophrenia and, to a lesser extent, in bipolar disorder (BP)." (PMID 21637803, 2011). "In this manuscript we present confirmation of earlier published associations between schizophrenia and the genes NRG1 and ERBB4." (PMID 17598910, 2007). "This study confirms previously published associations between schizophrenia and NRG1 and ERBB4, and points to three other members of the NRG and ERBB gene families (EGFR, NRG2 and NRG3) as potential schizophrenia susceptibility genes." (PMID 17598910, 2007). "However, the logistic regression model showed that the mutant homozygous (TT) genotype of the SNP rs839523 in ERBB4 tended to be significant (p = 0.063) with the schizophrenia status." (PMID 40977746, 2025). "A logistic regression model, taking the status of the participants (schizophrenia vs. healthy control) as the dependent variable adjusted over age and gender, showed that the mutant homozygous (TT) genotype of the SNP rs839523 in ERBB4 gene tended to significance." (PMID 40977746, 2025). "Functional studies suggest that rs839523 may influence alternative splicing of ERBB4, providing a mechanistic explanation for its involvement in schizophrenia pathophysiology." (PMID 40977746, 2025). "Therefore, the present study aims to investigate the potential association between the ERBB4 rs839523C/T and GABRB2 rs1816072 T/C polymorphisms, alongside selected environmental factors, in contributing to schizophrenia risk within the Lebanese population." (PMID 40977746, 2025). "Among the genes implicated in schizophrenia are gamma-aminobutyric acid A receptor beta 2 (GABRB2) and Erb-B2 Receptor Tyrosine Kinase 4 (ERBB4), which encode the Gamma-Aminobutyric Acid Type A Receptor Beta2 Subunit and the Erb-B2 Receptor Tyrosine Kinase 4, respectively." (PMID 40977746, 2025). "Interestingly, two susceptible genes linked to schizophrenia include NRG1, the gene encoding neuregulin-1 (NRG1), and ERBB4, which encodes receptor tyrosine kinase ERB-B4." (PMID 38563502, 2024). "This study suggests that enhancing ErbB4-nNOS signaling might alleviate GABAergic dysfunction in schizophrenia." (PMID 38396027, 2024). "Furthermore, Erbb4-nNos−/− mice manifest several schizophrenia-relevant behavioral deficits, including hyperactivity, impaired sensorimotor gating, and deficient working memory and social interaction." (PMID 38396027, 2024). "Given that both Erbb4 and nNos mutant mice exhibit behavioral phenotypes resembling schizophrenia-like, depression-like, and anxiety-like symptoms, we investigated whether the deletion of nNos from Erbb4-positive neurons resulted in behavioral deficits." (PMID 38396027, 2024). "Furthermore, another mechanism of NRG1/ErbB4 interactions to promote dendrite growth in mature interneurons is mediated by Kal7, whose encoding gene KALRN has been associated with schizophrenia." (PMID 36831241, 2023). "GOMAFU affects the splicesome by directly binding to splicing factor 1 for disrupted-in-schizophrenia-1 (DISC1) and v-erb-a-erythroblastic leukemia viral oncogene homolog 4 (ERBB4), two genes that play roles in the splicesome and were shown to contribute to schizophrenia." (PMID 36005827, 2022). "The ERBB4 and NRG-1 genes have been implicated as risk genes for the development of schizophrenia." (PMID 36119496, 2022). "Importantly, ErbB4 Cyt-1 receptor signaling and expression levels are altered in the dorsal lateral prefrontal cortex of persons with schizophrenia." (PMID 36012727, 2022).
schizophrenia (continued). "Similarly, mutations in genes involved in synaptic targeting by ChCs onto the AISs of pyramidal neurons including L1CAM, ERBB4, and FGF13 have been implicated in epilepsy, schizophrenia or intellectual disability." (PMID 34630048, 2021). "The direct and chronic disturbance of NRG1/ErbB4 signal transmission, such as the mutation of NRG1 or ErbB4 gene in some schizophrenia patients, can lead to the abnormality of glutamatergic synapses and nerve fibers, thus leading to developmental and functional abnormalities." (PMID 33897409, 2021). "As a specific ligand of receptor tyrosine kinase ErbB4, the structure and polymorphism of NRG3 are associated with neurodevelopmental disorders, including developmental retardation, cognitive impairment, autism and schizophrenia." (PMID 33897409, 2021). "Altered NRG1/ErbB4 signaling has been shown to contribute to NMDAR hypofunction in patients with schizophrenia and mice with NRG1 deletion have 16% fewer functional NMDAR than wild-type mice, whereas if a similar change occurs also in ErbB4 KO mice was not determined." (PMID 34899420, 2021). "We cannot exclude that ablation of NMDAR in ErbB4-positive cells induced at earlier time-points than in the present investigation may trigger schizophrenia-like abnormalities." (PMID 34899420, 2021). "Consistent with the hypotheses, the ligands for ErbB1 and ErbB4 are known to induce various behavioral deficits in the animal models relevant to schizophrenia." (PMID 31371697, 2019). "Furthermore, increased MIAT significantly decreased DISC1 (disrupted in schizophrenia 1), ERBB4 (v-erb-a erythroblastic leukemia viral oncogene homolog 4) and their alternatively spliced variants in SZ patient brains." (PMID 29534728, 2018). "These contradictory results could be explained by differences in the actual NRG1 and ErbB4 levels between early and late phases of schizophrenia, the severity of disease and the tissues sampled." (PMID 30574102, 2018). "In addition, several susceptibility genes for schizophrenia (e.g., DISC1, NRG1/ErbB4, and CRMP2), which are involved in either pre-synaptic DA release or post-synaptic D1R-related cascades, are similarly dysregulated by METH." (PMID 30061532, 2018). "Furthermore, genetic linkage and association studies led to the identification of two additional susceptibility factors related to schizophrenia, such as neuregulin-1 (NRG1) and its receptor ErbB4." (PMID 30061532, 2018). "ERBB4 has been extensively investigated as a vulnerability gene for schizophrenia." (PMID 28729842, 2017). "NRG1 function is mediated by a class of receptor tyrosine kinases including erbB4, and has been shown to associate with schizophrenia with altered NRG1/erbB4 signaling being reported in the brains of schizophrenia patients." (PMID 27895608, 2016). "Interestingly, deletion of ErbB4 only in fast-spiking interneurons produced neurophysiological and behavioural deficits consistent with schizophrenia endophenotypes." (PMID 27456313, 2016). "Given that NRG1, ErbB4, and DISC1 are schizophrenia-linked genes, these findings shed light on how independent risk factors may signal in a common developmental pathway that contributes to neural connectivity defects and disease pathogenesis." (PMID 27847649, 2016). "We have reanalyzed the association between COMT, ERBB4 or NRG1 and EEM in schizophrenia." (PMID 26242244, 2015). "Neuregulin-1 and ErbB4 mouse models have been extensively studied for functional and behavioral studies since they show schizophrenia-related behaviors including hyperactivity in the open field, defects in the Prepulse Inhibition (PPI) and deficits in fear conditioning and extinction." (PMID 26733804, 2015). "Moreover, mice with reduced levels of NRG1 or ErbB4 have exhibited behavioral alterations akin to those found in schizophrenia." (PMID 26029044, 2015).
schizophrenia (continued). "Nonetheless, a direct deficit in neurostructural dynamics caused by either Gomafu, DISC-1 or ErbB4 in patients with schizophrenia has not been established." (PMID 26483630, 2015). "Finally, several groups have assessed gene expression and proteins of NRG1 and ERBB4 in postmortem brains and have reported differences between schizophrenia and healthy control groups." (PMID 24478629, 2014). "Since both BDNF and NRG1 are implicated in the pathophysiology of schizophrenia, we examined whether the interaction between TrkB and ErbB4 is altered in schizophrenia." (PMID 25052836, 2014). "Furthermore, OLIG2 expression significantly correlated in cerebral cortex with CNP and ERBB4, suggesting that variation in OLIG2 confers susceptibility to schizophrenia as part of a network of genes implicated in oligodendrocyte function." (PMID 24478629, 2014). "A genetic variant of ErbB4 that is a risk factor for schizophrenia was shown to predict cortical GABA but not Glx concentrations." (PMID 24198792, 2013). "Indeed, two schizophrenia susceptibility genes encoding the trophic factor neuregulin 1 (NRG1) and its receptor ErbB4 (ERB4) have been shown to facilitate activity-dependent GABA release from PV-positive basket cells in the mouse prefrontal cortex." (PMID 21876820, 2011). "Indeed DISC1, neuregulin, ERBB4, FEZ1 or COMT knockout mice display many of the pathological and behavioural symptoms associated with schizophrenia." (PMID 22567321, 2011). "To further assess whether the aberrant behavior resulting from the genetic deletion of nNos from Erbb4-positive neurons is relevant to schizophrenia, we administrated clozapine (a second-generation antipsychotic medication) to both Erbb4-nNos−/− mice and control mice." (PMID 38396027, 2024). "In addition, susceptible genes, such as NRG1 (Neuregulin 1), and its receptor ErbB4, have received considerable attention as a plausible pathological mechanism of schizophrenia due to their crucial role in neurodevelopment and modulation of glutamatergic and GABAergic signaling." (PMID 35272593, 2022). "ErbB4 hyperactivation-directed treatment studies, such as those performed in T-Nrg1 mice, will allow to test the predictive validity of NC-Nrg1 mice and provide an entry point for the development of more potent treatment strategies that target specific endophenotypes in schizophrenia." (PMID 33871014, 2021). "However, treadmill running could still rescue schizophrenia-like phenotypes after knockout of ErbB4 in PV neurons, suggesting that ErbB4 in PV neurons in the DG is not required for the effect of exercise therapy in schizophrenia." (PMID 32117963, 2020). "Of these pathways, schizophrenia appears to have to strongest link to the Nrg/ErbB pathway, and SNPs in several of the genes encoding Nrg (NRG1, NRG2, NRG3, and NRG6) and all of the genes encoding ErbB receptors (EGFR, ERBB2, ERBB3, and ERBB4) have been linked to schizophrenia." (PMID 30618607, 2018). "Thus, the reported loss of MIAT transcript in schizophrenia may regulate the changes in DISC1 and ERBB4 splice variation seen in subjects with schizophrenia." (PMID 29657307, 2018). "In addition, ErbB4 expression is influenced by schizophrenia risk haplotypes, and individuals homozygous for the non-risk haplotype exhibit undetectable levels of ErbB4 in lymphoblastoid cells." (PMID 28646138, 2017). "Evidence of longer (i.e., slower) acoustic startle latency as indirect evidence of slowing of neural processing supports the underlying hypothesis that genetically determined alterations of the neuregulin-ERBB4 and glutamate signaling pathways play a role in the pathophysiology of schizophrenia." (PMID 28729842, 2017). "Further support for CSPG involvement in schizophrenia comes from molecular dissection of the neuregulin-ErbB4 pathway, which revealed an association with a genetic polymorphism in PTPRZ1, the gene encoding for receptor phosphotyrosine phosphatase beta/zeta (RPTPbeta) with schizophrenia." (PMID 26839720, 2016).
schizophrenia (continued). "Likewise, both NRG1 and its receptor ERBB4, which have been posited as promising candidates for schizophrenia as resulting from next-generation sequencing analyses, enhance synchronized oscillations of neurons in the prefrontal cortex, known to be reduced in schizophrenia, via inhibitory synapses." (PMID 27601987, 2016). "Thus, in human brains and in lymphoblastoid B-cell lines (LCLs) of subjects with schizophrenia, an ErbB4 risk haplotype (AGG; rs7598440, rs839523, rs707284) was found to be associated with elevated ErbB4 CYT-1 transcription and consequently raised expression of PIK3CD (p110δ)." (PMID 26877878, 2016). "Neuregulin 1-ErbB receptor signaling appears to play a critical role in the ontogeny of psychiatric disorders and this hypothesis has been supported by the identification of altered expression levels and/or function of NRG1, ErbB3, and ErbB4 in patients with schizophrenia." (PMID 26029044, 2015). "Moreover, Gomafu regulates genes also associated with schizophrenia such as DISC-1 and ErbB4 and these genes have been shown to be directly involved in neurostructural dynamics." (PMID 26483630, 2015). "Thus, we propose that ErbB4 signalling needs to be in an optimal range for proper network functioning and deviations above or below this range result in behavioural outcomes relevant to schizophrenia." (PMID 26656849, 2015). "Therefore, the understanding of NMDAR-NRG1/ErbB4 interactions during neural precursor migration may contribute to reveal the molecular and cellular basis of schizophrenia and of other neurodevelopmental disorders." (PMID 21991932, 2011). "The results of our first assessment of ErbB4 protein expression throughout the cerebrum of primates thus validate the use of mice with genetically altered ErbB4 expression for investigations on the biological pathways and neuronal networks involved in the etiology of schizophrenia." (PMID 22087295, 2011). "The association of schizophrenia and single-nucleotide polymorphisms (SNPs) of ERBB4 (v-erb-b2 erythroblastic leukemia viral oncogene homolog 4), enconding one of the receptors for NRG1 has been shown, thus suggesting that NRG1-ERBB signaling is involved in the pathogenesis of schizophrenia." (PMID 21637446, 2009). "These new findings suggest that observed associations between NRG1 and schizophrenia may be mediated through functional interaction not just with ERBB4, but with other members of the NRG and ERBB families." (PMID 17598910, 2007). "In sum, our results demonstrate that nNos deletion in Erbb4-positive neurons reduces GABA release and leads to schizophrenia-relevant behavioral deficits in adult mice." (PMID 38396027, 2024). "The prepulse inhibition (PPI) test, a measure of sensorimotor gating often impaired in schizophrenia patients, revealed a lower level of PPI in Erbb4-nNos−/− mice compared to controls, indicating impaired sensorimotor gating." (PMID 38396027, 2024). "A post-mortem study showed that in the PFC of schizophrenia patients, there was an increase in NRG1-induced ErbB4 activation and increased ErbB4/PSD-95 interaction, responsible for the suppression of NMDAR signaling activation." (PMID 36983018, 2023). "Moreover, alterations to the NRG1 and ErbB4 signaling pathways are involved in neuronal migration, regulation of synaptic plasticity and neural survival, which may be the neurobiological underpinnings of schizophrenia." (PMID 35337293, 2022). "This study highlights the role of the NRG1/ERbB4 and PI3K/AKT/mTOR signaling pathways in the neuroprotective effects of aripiprazole and sertindole on ketamine-induced schizophrenia in rats." (PMID 35876932, 2022). "In the present study, NVHL rats, which also exhibit schizophrenia-like behaviors, showed significant reduction in NRG-1 and p-erbB4 levels in the PFC, suggesting that NRG-1/erbB4 pathway in the PFC of NVHL rats was impaired." (PMID 36620856, 2022).